TMEM38A (transmembrane protein 38A)
Description:
Intracellular monovalent cation channel required for maintenance of rapid intracellular calcium release. Acts as a potassium counter-ion channel that functions in synchronization with calcium release from intracellular stores (By similarity). Opened by a change of voltage within the sarcoplasmic reticulum lumen (By similarity).
Synonyms: TRIC-A; TRICA; MGC3169
Tractability: Antibody: UniProt predicts a signal peptide or a membrane-spanning region.
Gene: Protein-coding gene on chromosome 19 (16,661,129 to 16,690,023, forward strand). Ensembl gene ENSG00000072954.
Subcellular location: Sarcoplasmic reticulum membrane; Nucleus membrane
Subcellular location (Human Protein Atlas): Nucleoplasm
Gene Ontology:
Molecular function: potassium channel activity; identical protein binding
Biological process: potassium ion transmembrane transport; regulation of release of sequestered calcium ion into cytosol; release of sequestered calcium ion into cytosol by sarcoplasmic reticulum
Cellular component: extracellular exosome; nuclear membrane; sarcoplasmic reticulum membrane; membrane; sarcoplasmic reticulum
Genetic constraint (gnomAD): Loss-of-function variants: 19 observed, 27.13 expected, observed/expected ratio (o/e) 0.7, 90% interval 0.49 to 1.03. The upper end of that interval is the gene's LOEUF score, 1.03, which puts it in group 4 of 6, group 1 being the genes least tolerant of losing a copy. Missense variants: 327 observed, 380.2 expected, observed/expected ratio (o/e) 0.86, 90% interval 0.79 to 0.94. Synonymous variants: 169 observed, 155.51 expected, observed/expected ratio (o/e) 1.09, 90% interval 0.96 to 1.24.
Homologues: Orthologues: chimpanzee TMEM38A (99% identical), macaque TMEM38A (98% identical), dog TMEM38A (96% identical), pig TMEM38A (95% identical), mouse Tmem38a (91% identical), guinea pig TMEM38A (88% identical), rat Tmem38a (80% identical), tropical clawed frog tmem38a (73% identical), zebrafish tmem38a (71% identical), rabbit TMEM38A (66% identical), Drosophila melanogaster CG4239 (31% identical), Caenorhabditis elegans tric-1B.1 (30% identical), and 1 more. Paralogues in human: TMEM38B (40% identical).
Diseases named in the same sentence as TMEM38A in open-access papers:
TMEM38A is named in the same sentence as 27 diseases in open-access papers, as found by Europe PMC text mining. Sharing a sentence is not in itself a finding about the gene and the disease. The quoted sentences say what the papers report.
cervical cancer (1 paper, 2023). A primary or metastatic malignant neoplasm involving the cervix. "Therefore, TMEM38A may modulate the efficacy of radiotherapy by affecting angiogenesis in cervical cancer through the PI3K pathway and the immune system." (PMID 38327905, 2023).
muscular dystrophy (1 paper, 2022). Muscular dystrophy (MD) refers to a group of more than 30 genetic diseases characterized by progressive weakness and degeneration of the skeletal muscles that control movement. "Intriguingly, mutations in PLPP7, TMEM38A, and TMEM201 have been identified in muscular dystrophy patients with an EDMD-like phenotype, which highlights the importance of these proteins in muscle disease." (PMID 36699009, 2022).
infection (1 paper, 2012). The state of being infected such as from the introduction of a foreign agent such as serum, vaccine, antigenic substance or organism. "Genes in regions associated with control of infection included a zinc finger cluster (ZNF192, ZSCAN16, ZNF389, and ZNF165; P = 0.001), C19orf42/TMEM38A (P = 0.047), and DLGAP1 (P = 0.092)." (PMID 23082221, 2012).
tumor (1 paper, 2023). "Thus, reduced expression of TMEM38A mediates decreased concentrations of Ca2+ in the tumor cells." (PMID 38203204, 2023).
TMEM38A also shares sentences with these, for which no sentence is quoted: Arrhythmia (2 papers); cardiac disease (2); cardiac hypertrophy (2); Hypertension (2); actinomycosis (1); Bradycardia (1); cancer (1); cardiac arrhythmia (1); carnitine deficiency (1); chronic heart failure (1); colon cancer (1); coronary artery disease (1); Emery-Dreifuss muscular dystrophy (1); fibrosis (1); glaucoma (1); heart failure (1); ischemia (1); leukemia (1); muscle disorders (1); myotonic dystrophy type 1 (1); osteogenesis imperfecta (1); prostate carcinoma (1); Treacher-Collins syndrome (1).